DCDC2 (doublecortin domain containing 2)
Diseases named in the same sentence as DCDC2 in open-access papers (continued):
Sharing a sentence is not in itself a finding about the gene and the disease.
epilepsy (1 paper, 2006). A brain disorder characterized by episodes of abnormally increased neuronal discharge resulting in transient episodes of sensory or motor neurological dysfunction, or psychic dysfunction. "Mutations in the human DCX gene result in abnormal neuronal migration, epilepsy, and mental retardation; mutations in RP1 are associated with a form of inherited blindness, and DCDC2 has been associated with dyslectic reading disabilities." (PMID 16869982, 2006).
Insulin resistance (1 paper, 2020). Increased resistance towards insulin, that is, diminished effectiveness of insulin in reducing blood glucose levels. "Moreover, under insulin resistance conditions, DCDC2 displayed increased association with the INSR, and the disruption of microtubules led to complete loss of this interaction." (PMID 33458251, 2020).
neuronal migration disorders (1 paper, 2013). "In comparison, DCDC2 is not an adhesion molecule, but is cytoplasmic and modulates microtubule function during development in a manner similar to other genes of the doublecortin family associated with neuronal migration disorders." (PMID 23724130, 2013).
reading (1 paper, 2021). "We measured motion perception in two groups of dyslexics, with (+) and without (–) deletion in DCDC2, matched for age, IQ, and reading disabilities." (PMID 34228165, 2021).
reading disorder (1 paper, 2016). A learning disability involving difficulty reading resulting primarily from neurological factors which affect any part of the reading process. "A number of “candidate genes” for reading disorders have been identified, for example dyslexia susceptibility 1 candidate 1 (DYX1C1), roundabout Drosophila homolog 1 (ROBO1), doublecortin domain-containing protein 2 (DCDC2) and KIAA0319." (PMID 27551971, 2016).
renal fibrosis (1 paper, 2024). A final common manifestation of a wide variety of chronic kidney diseases characterized by glomerulosclerosis and tubulointerstitial fibrosis. "Recessive pathogenic variants of DCDC2 are known to cause a renal-hepatic variant of nephronophthisis-related ciliopathies that is characterized by severe early onset liver fibrosis and renal involvement with tubular defects, renal fibrosis, cyst formation and eventually CKD." (PMID 38124660, 2024).
cancer (6 papers, 2013 to 2025). A tumor composed of atypical neoplastic, often pleomorphic cells that invade other tissues. "Given that few studies have reported the regulation of cancer progression by DCDC2, we investigated the effect of DCDC2 overexpression in CRC." (PMID 36739270, 2023). "DCDC2 was revealed to be hypermethylated (methylation value 0.846, range 0–1.0) in cancer tissue, compared with adjacent normal tissue (0.212) by methylation array in the 68-year-old female patient." (PMID 24034596, 2013). "DCDC2 has contrasting effects on tumor progression in diverse cancer types." (PMID 36739270, 2023). "However, few studies have explored the function of DCDC2 in cancer." (PMID 40533767, 2025). "However, there are only a few reports of the relationship between DCDC2 and cancer." (PMID 24034596, 2013). "Furthermore, DCDC2 showed tissue-specific high expression in ICC tissues, among all the normal tissue types (GTEx database) and pan-cancer types (TCGA database)." (PMID 40533767, 2025).
tumor (4 papers, 2013 to 2025). "In vivo assays revealed that treatment with Lag-3 antibodies negated the tumor growth enhancement associated with Dcdc2 overexpression, while Fgl1 knockdown blocked the efficacy of Lag-3 antibodies." (PMID 40533767, 2025). "The results showed that LAG-3 antibody treatment abolished the enhancement of tumor growth induced by DCDC2 overexpression in humanized mice, both in the tumor volume and the tumor weight." (PMID 40533767, 2025). "Our findings position anti-DCDC2 autoantibody as a promising diagnostic biomarker for ICC, associated with poor prognostic outcomes, and elucidate its critical role in tumor growth and immune evasion through its interaction with ENO1." (PMID 40533767, 2025). "We collected 13 ICC tumor samples and performed qPCR to evaluate the expression of DCDC2 and FGL1, alongside an analysis of their correlation." (PMID 40533767, 2025). "Doublecortin domain-containing 2 (DCDC2) is a candidate tumor suppressor gene detected by this triple combination array analysis." (PMID 24034596, 2013). "The DCDC2 expression index was calculated as the value of the tumor tissue expression level divided by that of the expression level of the adjacent normal tissue." (PMID 24034596, 2013). "We confirmed reduced expression of DCDC2 mRNA in tumor tissue by semi-quantitative RT-PCR in the case whose samples were used for the array analysis." (PMID 24034596, 2013). "Overall, 41 of the 48 (85.4%) tumor samples displayed DCDC2 promoter hypermethylation, whereas only 9 of 48 samples showed hypermethylation in the normal samples." (PMID 24034596, 2013). "Besides the top-ranked fold change (CCA/Non-tumor) of DCDC2 expression levels in these two cohorts, the mRNA levels of DCDC2 of CCA tissues were also in remarkably high levels." (PMID 40533767, 2025). "Notably, DCDC2 has been identified as a candidate tumor suppressor gene in HCC through triple combination array analysis." (PMID 38658618, 2024). "In the future, it might be applied in the clinical setting for HCC patients who have methylated DCDC2 in their tumor tissue." (PMID 24034596, 2013). "The expression of DCDC2 in tumor tissues was decreased in methylated cases (P = 0.048)." (PMID 24034596, 2013). "MSP revealed hypermethylation of the promoter region of DCDC2 in 41 of the tumor samples." (PMID 24034596, 2013). "Thus, hypermethylation of DCDC2 was significantly more frequent in tumor tissues (P < 0.001)." (PMID 24034596, 2013). "Next, immunofluorescence (IF) and immunohistochemical staining (IHC) assays were performed to examine the expression and distribution of the DCDC2 protein in ICC and Non-tumor tissues." (PMID 40533767, 2025). "In vivo assays confirmed the promoting effects of DCDC2 on the tumorigenicity of ICC cells, with both increased tumor volumes and tumor weight." (PMID 40533767, 2025). "The present study uncovered a DCDC2/ENO1/FGL1/LAG-3 axis and communication between ICC tumor cells and CD8+ T cells." (PMID 40533767, 2025). "Consistently, DCDC2 significantly promoted both the volume and the weight of ICC tumor that generated in the humanized mice." (PMID 40533767, 2025). "Thus, we also explored whether DCDC2 could influence tumor immunology." (PMID 40533767, 2025). "In the allograft tumor-bearing model, we observed that the function of NK cells was decreased in the Dcdc2 overexpression group (data not shown)." (PMID 40533767, 2025).
genetic disorder (1 paper, 2018). "DCDC2 is a newly identified genetic disorder causing neonatal sclerosing cholangitis." (PMID 30367658, 2018).
DCDC2 also shares sentences with these, for which no sentence is quoted: hepatocellular carcinoma (3 papers); kidney disease (3); breast carcinoma (2); cystic fibrosis (2); lung carcinoma (2); prostate carcinoma (2); sclerosing cholangitis (2); autosomal recessive deafness (1); Bardet-Biedl syndrome (1); biliary cirrhosis (1); childhood apraxia of speech (1); congenital hepatic fibrosis (1); Dyscalculia (1); gallbladder cancer (1); intrahepatic cholangiocarcinoma (1); learning disorders (1); major depressive disorder (1); Miscarriage (1); neurological disease (1); renal cysts and diabetes syndrome (1); Wilson disease (1).